IL6 (interleukin 6)
Diseases named in the same sentence as IL6 in open-access papers (continued):
Sharing a sentence is not in itself a finding about the gene and the disease.
tumor (continued). "IL-6 signaling shifts the balance in the tumor microenvironment from being pro-tumorigenic to anti-tumorigenic." (PMID 37122749, 2023). "The correlation between elevated serum IL-6 levels and advanced tumor stages, increased tumor size and decreased survival of patients with CRC has also been documented." (PMID 37047623, 2023). "Albumin synthesis decreases in response to the production of some inflammatory factors involved in tumor immunity and the acute phase response, such as tumor necrosis factor, interleukin-6, and C-reactive protein (CRP)." (PMID 37576904, 2023). "In the tumor microenvironment, neutrophils secrete proteases, cytokines, and growth factors, including interleukin (IL)‐6, IL‐8, epidermal growth factor and vascular endothelial growth factor, that lead to tumor cell activation, invasion, and metastasis." (PMID 36806947, 2023). "IL-6 facilitates the interaction between tumour cells and CAFs by enhancing fibroblast activation and tumour cell proliferation." (PMID 37927475, 2023). "Tumour‐derived mediators induce M2 cell polarisation, IL‐6 expression in macrophages and neutrophils through SIRPα/SHP‐1/p38 MAPK/STAT3 signalling." (PMID 36419386, 2023). "Immunohistochemistry and enzyme-linked immunosorbent assay were performed to detect SIRT3 expression and the expression levels of IL-1β, TNF-α, and IL-6, respectively, in tumor tissues." (PMID 37747648, 2023). "IL-6 signaling is closely related to MDA-MB 231 cell growth and in vivo malignancy; blocking its pathway was associated with inhibition of tumor growth and invasion." (PMID 36794014, 2023). "Many stimuli have been reported in the literature, including IFN-γ, GM-CSF, and TNF-α inducing macrophages to M1 polarization for anti-tumor function, and IL-1β, IL-6, IL-10, and IL-4 inducing macrophages to M2 polarization for pro-tumor function." (PMID 37063892, 2023). "Collectively, ENO1 promotes tumor cell migration and invasion by orchestrating IL-6 secretion of macrophages via a dual mechanism, thus forming a positive feedback loop to promote OSCC progression." (PMID 36614179, 2023). "Pro-inflammatory cytokines such as interleukin (IL)-6 and IL-1β promote tumor proliferation and suppress immune responses to tumor cells, contributing to tumor progression." (PMID 37686634, 2023). "In spite of the wide range of evidence for EMT induced by IL-6 signaling in certain tumor types, the links between IL-6 and EMT in EOC are poorly documented at present." (PMID 36814597, 2023). "Many studies have demonstrated that IL-6 and TNF-a enhance tumor cell adhesion and that this is associated with an increased expression of ICAM-1 and VCAM-1 by mesothelial cells." (PMID 38068319, 2023). "TME, known as an important prognostic marker in cancer patients, features with various pro-inflammatory cytokines including tumor necrosis factor-α (TNF-α), IL-1β and IL-6 to build a tumor-supportive microenvironment to escape immune surveillance." (PMID 37047623, 2023). "Studies have shown that hypoxia upregulates the TAMs-derived cytokines such as vascular endothelial growth factor (VEGF), TGF-β, CCL18 and IL-6, which were involved in tumor progression and metastasis." (PMID 37884960, 2023). "It was demonstrated that IL-6 contributed to the acceleration of tumor progression and increased the migration of CRC cells." (PMID 37509653, 2023). "Neutralizing IL-6 with antibodies, for instance, sensitized multiple tumor types toward distinct chemotherapeutic regimens." (PMID 37900569, 2023). "Activation of the IL-6/STAT3 signaling pathway promotes tumor metastasis, and IL-17 released from CD8+ T cells also stimulates cutaneous tumor growth." (PMID 37628724, 2023). "In vivo, we demonstrated that serum IL-6 concentration in mice showed a stronger correlation with αSMA positive IHC than with tumor weight, indicating that the amount of IL-6-producing CAFs in the TME influences tumor development." (PMID 36764954, 2023).
tumor (continued). "Interleukins such as IL-6 and IL-10 also play significant roles in modulating the tumor microenvironment through the promotion of inflammation or immunosuppression." (PMID 37760801, 2023). "CAFs were activated fibroblasts in tumor tissues and were demonstrated to be involved in metastasis by releasing various cytokines, including IL-6." (PMID 37481520, 2023). "Other mechanisms that lead to the continuous activation of the JAK-STAT signaling pathways include extracellular signals by excessive cytokine expression, such as interleukin-6 upregulation by tumor cells and tumor microenvironment." (PMID 37175040, 2023). "In this role, IL-6 opposes tumor growth by mobilizing lymphocytes and anti-tumor T cell immune responses against tumor expansion." (PMID 36768935, 2023). "Their research unveiled the significant influence of fibroblasts, which secrete paracrine cytokines such as IL-6, on tumor survival and growth." (PMID 37946275, 2023). "Tumour-derived cytokines, including IL-6, IL-10, and transforming growth factor (TGF)-β1, also hinder tumour antigen processing and presentation by DCs." (PMID 37454231, 2023). "Primary tumor-secreted IL-6 induced soluble IL-6Rα expression in skeletal muscle, which was transported to the subcutaneous adipose tissue." (PMID 37222464, 2023). "Neutrophils secrete IL-6, IL-8, and IL-12 to promote the tumour inflammatory microenvironment, and the proliferating tumour cells in turn stimulate neutrophils, forming a vicious circle." (PMID 37036321, 2023). "Tumour-adjacent tissues in ER− disease displayed activated inflammation pathways including IL-6 and IFN gamma with increasing BMI." (PMID 37173907, 2023). "In line with this, IL-6 is produced by monocytes, tumor cells, CAFs, endothelial cells, and cells specific to a diseased state." (PMID 37893079, 2023). "Similar findings were observed in GBM; RBPJ can increase GBM cell proliferation, invasion, stemness, and tumor initiating ability by enhancing the activation of the IL‐6/STAT3 pathway." (PMID 37576862, 2023). "Nevertheless, in peritoneal metastasis tumor model, various cytokines especially IL‐6 showed a rise in the CAR‐T/FreeSwitch group." (PMID 36755195, 2023). "Activated tumor cells in the feedback loop decreased glycolysis by increasing oxidative phosphorylation via IL-6." (PMID 37409257, 2023). "The elevated levels of IL-6 in serum and tumor sections were identified in LDC@ZnP-MA + NIR treated mice, resulting in a favorable infiltration of CTLs in tumor." (PMID 37752555, 2023). "The IL‐6 axis is frequently dysregulated in cancer, which promotes pro‐tumor effects such as cancer growth, migration, and metastasis by activating the IL‐6/JAK/STAT3 pathway." (PMID 36632988, 2023). "In cancer patients, IL-6 is generally considered a pro-inflammatory cytokine, promoting tumor cell proliferation and metastasis." (PMID 37760634, 2023). "IL-6 in the TME also enhances tumor cell autophagy and promotes tumor cell survival in CIC while promoting the death of internalized lymphocytes." (PMID 37790755, 2023). "As an immunomodulator, IL-6 can stimulate tumor cell proliferation, reduce apoptosis, induce drug resistance, and promote bone metastasis." (PMID 37151385, 2023). "Meantime, S100A9 activates angiogenesis via an autocrine effect on tumor cells and a paracrine effect on stromal cells in oral cancer, similarly accompanied by IL6 production." (PMID 37701037, 2023). "In the present study, we observed that patients with high expression of IL-6 in their tumor had worse disease-free survival compared with those with low expression of IL-6 in tumor." (PMID 36635302, 2023). "Interleukin 6 is known to suppress hepatic ketogenesis in tumor-bearing mice, leading to higher glucocorticoid secretion, immunosuppression, and failure of the immunotherapy." (PMID 37686288, 2023). "Hypoxia generally causes cell necrosis, leukocyte infiltration, and the release of TNF-α and IL-6 in tumor cells." (PMID 36837487, 2023).
tumor (continued). "The proportion of patients with low IL‐6 level (<4.285 pg/mL) in the subgroup who undergone tumor relapse during consolidation therapy within 2 years was decreased compared with those who maintained long‐term CR after treatment cessation for over 2 years." (PMID 38020717, 2023). "The high expression of EGFRvIII influenced by IL-6 promoted the proliferation of tumor cells in vitro, and IL-6 significantly influenced the expression of Bcl-XL and STAT3 in another tumor." (PMID 38201528, 2023). "The role of IL-6 and IL-8 secreted by MSCs as inflammatory chemokines on tumor progression has been demonstrated in some cancer models." (PMID 38022534, 2023). "A-FABP released from adipose tissue promotes tumor stemness by activating the IL-6/STAT3/ALDH1 pathway." (PMID 36880535, 2023). "In a murine model of pancreatic cancer, IL-6 alters the balance of Th17 cells in the tumor microenvironment and the induction of Th17 cells in the tumor microenvironment to inhibit tumor growth." (PMID 37686343, 2023). "Recent studies have shown that pro-inflammatory cytokines such as interleukin (IL)-1β, tumor necrosis factor (TNF)-α, and IL-6 in a tumor microenvironment contribute to the development and metastasis of cancers through the immune escape of cells [2, -4]." (PMID 37501379, 2023). "To closely follow the course of events, we also tested the serum from ETBF-infected, 086Mut-infected, and sham control 4T1 tumor-bearing mice at day 3 and 4 weeks post-tumor cell implantation for the levels of early-response cytokines, IL6 and TNFα." (PMID 37503343, 2023). "To date, there is emerging evidence also illustrating the roles of some ILs, including IL-6 and IL-10, in inhibiting antitumor immune responses and promoting tumor progression after incomplete ILTs." (PMID 36831664, 2023). "We demonstrate that XIST acts as a master regulator of cytokine-cytokine receptor interactions and drives IL-6 expression from ALDH- bulk tumor cells to regulate ALDH+ CSCs in a paracrine fashion." (PMID 36922677, 2023). "In this study, we determined the expression levels of GPR84, KLF7, IL-6, p21 in tumor tissues of patients with PCa and obesity with primary PCa tumor-bearing mouse model." (PMID 37170248, 2023). "We found the expression level of PCNA and p-STAT3 was decrease greatly in MDG group (p < 0.05 and p < 0.05) compared with MD group, indicating the inhibition of tumor proliferation and NF-κB/IL-6/STAT3 signaling downstream protein." (PMID 37818040, 2023). "We observed that non-responders showed elevated levels of proinflammatory mediators, such as IL-1RA, IL-6, IL-8 and to lesser extent IL-10, which are associated with STAT3 activation and tumor immunosuppression." (PMID 38259453, 2023). "Once IL-6 trans-signaling occurs, it induces the expression of pSTAT3 and pERK activity in pre-malignant cells, probably leading to tumor development." (PMID 38275386, 2023). "In clinical samples, IL-6 expression was significantly correlated with α-smooth muscle actin expression, and high IL-6 cases showed tumor immunosuppression." (PMID 36764954, 2023). "PC cells are able to rearrange the tumor-bone microenvironment by secreting a plethora of paracrine factors, such as interleukin 6 (IL6), that modulate the activity of bone-forming osteoblasts, and bone-resorbing osteoclasts." (PMID 36614201, 2023). "In breast tumors, MDSCs exert their potent immunosuppressive functions through several pathways: (a) STAT3-NF-Κb-IDO, which is activated by tumor-derived IL-6 to activate STAT3 in MDSCs." (PMID 36982282, 2023). "In our initial transitional monocytes system that mimic the responses of tumor-associated monocytes/macrophages under IFN-based therapy, we have demonstrated the involvement of IL-4 and IL-6 in mediating the IFN-elicited, unconventional M2 program." (PMID 36726024, 2023). "EMT prominently generates CAFs that further secrete factors synergizing with tumor metastasis, such as IL-1β, IL-6, IL-8, and matrix metalloproteinases." (PMID 37946275, 2023).
tumor (continued). "Many cytokines including interleukin-6, interleukin-8, and tumor necrotic factors have been concluded as strong indicators for COVID-19 infection." (PMID 37222789, 2023). "Targeting IL-6 for cancer therapy remains an unexploited niche despite the central role of IL-6 in tumor inflammatory responses." (PMID 37887354, 2023). "It was also reported that incomplete RFA of a target tumor can sufficiently stimulate residual tumor cells to induce accelerated growth of distant tumors via the IL-6/c-Met/HGF pathway and VEGF production." (PMID 37952066, 2023). "Accordingly, IL-17A/F secreted by pathogenic Th17 cells has been shown to contribute to the growth and metastasis of numerous cancers via increased secretion of IL-6 by tumor cells and tumor-stromal cells, resulting in Stat-3 activation." (PMID 37296927, 2023). "Six out of 18 chemokines/cytokines assessed were significantly decreased in the ascites from NLRC5+ tumor-bearing mice, including IL-6, IL-10, IL-12, CXCL10, CCL5, and to a greater extent, CCL2." (PMID 38235131, 2023). "RORγt+ Tregs are also required to suppress Foxo3 in tumor-infiltrating DCs, leading to the establishment of a IL-6 rich, pro-tumor microenvironment." (PMID 37197653, 2023). "In the tumor microenvironment, there are different levels of proinflammatory cytokines such as IL-1β, IL-6, IL-8, and TNF-α." (PMID 38137862, 2023). "In sum, IL-6 plays a role in controlling cancer cell dormancy or awakening, depending on the interaction between the stage of the tumor cell progression and the TME." (PMID 37173977, 2023). "By inhibiting the STAT3/PKM2/SNAP23 pathway, ATL I reduces the production of IL-6 and extracellular vesicles in C26 tumor cells and can be used to treat cancer cachexia." (PMID 37241729, 2023). "Four clinical (CEA, cT stage, cN stage, and tumor length), three serological (interleukin (IL)-6, IL-8, and osteopontin), and one imaging (maximal standardized uptake value (SUVmax)) predictor(s) were selected." (PMID 37568760, 2023). "M1 macrophages generally contribute to tumour cell destruction by either engulfing or by releasing cytotoxic factors and pro-inflammatory cytokines IL-6, IL-12 and TNF-α." (PMID 37612278, 2023). "IL‐6/JAK/STAT3 signaling can drive tumor cell proliferation, invasion, and metastasis in the TME, and strongly inhibit the antitumor immune response." (PMID 38063246, 2023). "While, the immune-related pathways, tumor-related pathways (such as epithelial–mesenchymal transition, IL6 JAK STAT3 signaling, and G2M checkpoint) and inflammation-related pathways were downregulated." (PMID 36445533, 2023). "In TNBC, hepatic leukemia factor (HLF) transactivated gamma-glutamyltransferase 1 (GGT1) promote the ferroptosis resistance and interactive dialogue between TNBC cells, and TAMs promotes sustained activation of HLF in tumor cells through the IL-6–TGF-β1 axis." (PMID 37681908, 2023). "The IL-1β is able to stimulate the secretion of IL-6 by fibroblasts, which in turn promotes tumor angiogenesis, metastasis, and invasion through EMT, demonstrating a direct correlation with the neovascularization process." (PMID 37445908, 2023). "Plausible mechanistic explanations for these observations involve tumor-induced inflammation and subsequent cytokine production, particularly IL-6 and IL-8, which are known to play a pivotal role in the epithelial-mesenchymal transition (EMT)." (PMID 37880772, 2023). "During CAR T therapy, DAMPs leakage by pyroptotic tumor cells activate macrophages and induce the release of IL-1β and IL-6, triggering CRS, highlighting the involvement of pyroptosis-DAMPs axis in CARTOX." (PMID 36761757, 2023). "The present study aimed to investigate the expression of serum/tissue IL-6, IL-8 and IL-10 in canine mammary gland tumors using Enzyme linked immunosorbent assay(ELISA), Western blot and Immunohistochemistry assay(IHC) to determine whether it is associated with tumor progression." (PMID 36693957, 2023).
tumor (continued). "IL-6 stimulates the epithelial‐to‐mesenchymal transition (EMT) process of tumor cells, contributing to the malignant progression of tumors in the late stages of cancer development." (PMID 37385076, 2023). "IL-6 can affect neoplastic progression, acting as an autocrine tumor growth factor as well as evading immunological surveillance." (PMID 37173873, 2023). "IL-6 is a pleiotropic cytokine with diverse biological activities, most notably related to tumor-promoting processes." (PMID 37696858, 2023). "Our results indicate that epigenetic priming mediates the rapid secretion of key tumor-derived cytokines known to augment T and NK cell activation and cytotoxicity, including IL-6, IP-10 (CXCL10), KC (CXCL1), and RANTES (CCL5)." (PMID 37627156, 2023). "These genes, including IL6, ICAM-1, and CXCL14, are associated with immune cell signaling, tumor progression, and metastasis, indicating that tumor cells induce a highly specific gene expression signature to enforce their tumorigenic properties in the TME." (PMID 36868311, 2023). "Anti-IL-6 antibodies halt tumor growth in vitro and in vivo, however, clinical application of anti-IL-6 therapies does not appear to lengthen survival in metastatic PCa patients." (PMID 36614308, 2023). "Dual blockade reduced pro-metastatic and pro-inflammatory transcription factor expression in tumor samples, and reduced post-operative increases in serum levels of IL-6 and CRP." (PMID 37426669, 2023). "A previous study has shown that, interleukin-6 (IL-6), a tumour-promoting cytokine in the TME, can induce microglia M2-like polarisation by increasing ARG1 expression." (PMID 37462801, 2023). "Recently, we discovered that IL-6 produced in the tumor microenvironment augmented arginase-1 (ARG1) activity, and blockade of ARG1 significantly reduced tumorigenesis in a tumor-bearing model." (PMID 36639644, 2023). "This destruction releases tumor antigens and increases concentrations of IL-6, TNF-α, and IFN-γ, stimulating dendritic cell maturation, NK cell activation, and T cell response promotion." (PMID 37514190, 2023). "We observed that the lactate concentration in tumors, tumor weight, and IL-6 concentration in tumors were significantly decreased by FX11 treatment." (PMID 37733442, 2023). "Brown or yellow colour indicated positive IL-6, IL-8 and IL-10 staining on the cell membrane or in the cytoplasm of tumor cells." (PMID 36693957, 2023). "IL‐6 is a major tumor‐interrelated inflammatory cytokine, whose production and exudation by multiple types of cells involving the tumor cells." (PMID 37326149, 2023). "BM MSCs fused with HNSCC cells develop sustainable drug resistance mediated through IL-6 and epigenetic imprinting, and impart more aggressive in vivo tumor growth." (PMID 37046676, 2023). "In examining select cytokines in the core and edge regions, we observed an elevation in TNF-α, IL-1β, and IL-6 in the edge compared to the tumor core." (PMID 37752585, 2023). "The increased level of circulating IL-6 has been related to metastatic disease and poor prognostic outcome in cancer patients with diverse histological tumor types, as reported in numerous studies." (PMID 38258065, 2023). "In solid tumours, the release of TGF-β and IL-6 likely suppresses the proliferation and migratory properties of DCs, resulting in interference with tumour-directed priming of cytotoxic T cells." (PMID 37240052, 2023). "It is induced by many inflammatory cytokines like TGF-β, TNF-α, IL-1, and IL-6, influencing inflammation in cancer, by which the desmoplastic response of tumors involves an interplay between the invading tumor cells and the altered extracellular matrix." (PMID 36742380, 2023). "Increased CD90 expression is associated with other pathologies such as cancer, where it induces inflammation and increases tumour progression by promoting IL-6 secretion." (PMID 37060003, 2023).